CD4 (CD4 molecule)
Diseases named in the same sentence as CD4 in open-access papers (continued):
Sharing a sentence is not in itself a finding about the gene and the disease.
co-infection (continued). "Our study therefore suggests that in HIV patients with a low CD4+ T cell count, a HCMV co-infection generates an aggravated IFNγ response which thereby leads to the activation of the CXCL9/10/11-CXCR3 chemokine axis." (PMID 35538132, 2022). "For example, a clinical trial conducted in Côte d’Ivoire by Kouamé in 2021 focused on people with low CD4 cell counts and found a higher impact of HIV and HBV co-infection on mortality." (PMID 35624437, 2022). "Risk factors associated to the loss of LTNP status was: higher age at diagnosis and the increase of VL, whereas the increase of CD4+ T cell counts and CD4/CD8 ratio, the initial EC-LTNP phenotype and HCV coinfection were protective factors." (PMID 36175445, 2022). "Early studies found that expression of the HIV co-receptor CCR5 was reduced on CD4+ and CD8+ T cells in individuals with HPgV-1 and HIV co-infection compared to HIV mono-infected." (PMID 35707535, 2022). "Overwhelming evidence substantiates that age, baseline CD4+ T lymphocyte level, HCV co-infection and other factors can affect the immune reconstitution of patients." (PMID 36195585, 2022). "The objective of this study was to investigate the expression of FOXP3+ Treg cells in leprosy skin lesions and to correlate their clinical forms, laboratory characteristics (CD4, CD8, and CV), and the immune reconstitution syndrome in HIV-leprosy co-infection." (PMID 34748560, 2021). "The risk factors for coinfection with HBV in HIV-positive individuals may vary in several aspects, including patient age, body mass index, sex, geographical location, current ART regime and duration, key population category, HIV viral load, marital status, and CD4+ T cell count." (PMID 35222296, 2021). "Given the central role of CD4+ T cells in coordinating antiviral immune responses, it is not surprising that the immune response to HCV in the context of an HCV/HIV coinfection is compromised." (PMID 34456931, 2021). "This suppression of viral replication results from an increase in CD4 cells and increases the survival of children with TB/HIV co-infection." (PMID 34191846, 2021). "Spontaneous sero-reversion can occur due to having a low CD4 count (<200/mm3) and is also a prime marker for HIV-HBV coinfection." (PMID 35222296, 2021). "In addition, a recent systemic review reported that co-infection with schistosomes increased the risk of HIV-1 acquisition by 4-fold, through mechanisms involving increased expression of CCR5 and CXCR4 HIV-1 co-receptors on CD4+ T cells and cervical mucosa lesions." (PMID 34220854, 2021). "In our study, the main risk factors associated with CKD development were age > 30 years old, more advanced HIV disease (with high viral load and lower CD4+ T cells count), and TB and HCV coinfections." (PMID 34556049, 2021). "Women with symptomatic HIV clinical stage III (AOR =2.06, 95% C.I (0.75-5.61), with CD4 cell count below 250 (AOR = 1.14, 95% C.I (0.57-2.28), and with co-infections (AOR= 1.04, 95% C.I (0.40-2.71) also suffered from depression." (PMID 32742296, 2020). "Accordingly, co-infection with human immunodeficiency virus (HIV), which impairs CD4+ T cells during its reproduction, is one of the major reactivation factors." (PMID 32753607, 2020). "We also aimed to explore the impact of HCV coinfection on the immune response to TB by analyzing the levels of immune activation markers IFN-γ, CD38, and HLA-DR on TB-specific CD4+ T cells." (PMID 31952232, 2020). "Some of these markers are lower current CD4 T+ cell count (measured continuously, lower nadir CD4 T+ cell count, as well as HCV coinfection, low body mass index (BMI), high BMI, lipodystrophy, or depressive symptoms." (PMID 32187205, 2020). "To investigate the potential impact of HIV-1 co-infection on TIIC infiltration into KS tissues, we compared staining for CD8, CD4, B, and NK cells between EpKS and EnKS patients." (PMID 32391124, 2020).
co-infection (continued). "CM patients with lower baseline CSF WCC, CSF protein concentration or CD4/CD8 ratio, and those with altered mentation or HIV coinfection were more likely to have poor clinical outcome (P<0.05)." (PMID 32758162, 2020). "In the context of HIV co-infection, effective treatment with cART suppresses HIV replication and restores the total CD4+cell count." (PMID 31467339, 2019). "Further studies are needed to examine the effects of CD4 cell count level HIV antiretroviral regimens, and obesity among TB HIV co-infection and DM." (PMID 31664936, 2019). "Predictors that decrease the likelihood of protective seroconversion include low CD4 T-cell count, detectable HIV viral load, infection, and co-infection with HCV." (PMID 30934708, 2019). "Previous studies showed that the co-infection of acute bacterial STI (e.g., Syphilis) resulted in increased HIV viremia and a decrease in CD4 counts." (PMID 30822343, 2019). "Although beyond the scope of this current study, it will be important to address the roles of CXCR3 ligands in mediating CD4+ T cell migration and HIV-1 mucosal transmission when an animal model become available to study HSV-2 and HIV-1 co-infection." (PMID 30619292, 2018). "Effect of cART on CD4+ T-cell count, CD4/CD8 ratio and HIV viral load in HIV-HBV and HIV-HCV coinfection." (PMID 30192795, 2018). "Flow cytometric profiling and ELISPOT assays of isolated CD4+ T cells also showed that Plasmodium co-infection abrogates infiltration of activated (LFA-1+) and IFNγ-secreting CHIKV-specific CD4+ T cells into the joints." (PMID 30254309, 2018). "This study however noted no statistical significance between the degree of immune-suppression as reflected by CD4 counts and HBV co-infection." (PMID 29338763, 2018). "Apart from expected significant differences in baseline and current CD4 T-cell counts as well as CD4:CD8 ratio between the oIR and sIR groups, all other HIV-related clinical variables and hepatitis B/C co-infection status were comparable in the two groups." (PMID 30250162, 2018). "The full model included the participant’s age, race/ethnicity, CD4+ cell count, HBV co-infection, HCV co-infection, education and smoking status." (PMID 33521162, 2018). "Comparison with data from adult cohorts however, indicated a better-than-expected rate of CD4:CD8 ratio recovery, despite widespread CMV coinfection, that was supported by ART initiation earlier in childhood." (PMID 29465561, 2018). "Accordingly, the hazard distribution of ART clients for sex, baseline CD4 count and history of Tb/HIV co-infection was statistically significant." (PMID 29912974, 2018). "Among HIV-positive subjects, 70% were smokers, 49% reported recent cocaine use, 44% had current CD4 counts <300 cells/μl, 72% had nadir CD4 counts below 300 cells/μl, and 42% had HCV co-infection." (PMID 29740045, 2018). "Furthermore, if CD4+ monitoring was limited to once annually in patients without HCV co-infection and twice annually in patients with co-infection, 506 CD4+ measurements could be cut and the total annual expenditure for CD4+ examinations could decrease by 50% (2nd scenario)." (PMID 28166729, 2017). "This difference was comparable to those observed using ELISPOT and flow cytometry, and collectively suggest that in the setting of HIV/CMV co-infection, HIV MDSC restrict CMV-specific CD4+ T cell IFNγ production." (PMID 28338007, 2017). "This is the first study to explore the influence of HHV co-infections on K/T ratio in treated HIV-infected participants and assess its impact on CD4 T-cell recovery in a developing country setting where HHV infections are highly prevalent." (PMID 29016635, 2017). "In this context, CD4 levels were lower for occult patients compared to both HIV mono-infection and HIV/HBV co-infection, with ~90% having a CD4 T-cell count of <250 cells/mm3." (PMID 28591184, 2017).
co-infection (continued). "Mean hematological profiles by HIV/malaria co-infection and HIV only were compared using independent t-test and mean CD4 count tested by mixed design repeated measures ANOVA." (PMID 28346490, 2017). "In conclusion, co-infection with multiple HHV is common in treated HIV-infected participants in the developing country setting and significantly impacts CD4 T-cell recovery." (PMID 29016635, 2017). "In both states, there was higher hazard for mortality in patients with CD4 count 100 cells/mm3 or less at ART initiation, males, and in patients with TB co-infection." (PMID 27729025, 2016). "We retrospectively reviewed the data of 178 HIV patients and determined the prevalence of thyroid dysfunction and the relationship between thyroid hormone levels, CD4 cell count, HIV-1 duration, HAART duration/regimens, and HBV/HCV coinfection." (PMID 27200374, 2016). "However, clinical information, such as maternal HCV viral load, mode of delivery of infants, infant liver function markers, risk factors (such as HBV co-infection) and laboratory results (such as CD4 cell counts and HIV viral loads) were not available for our study." (PMID 28879101, 2016). "In addition, our study confirms the published findings that HIV infection increases in risks for TB, but also provides new association data suggesting that hierarchy low CD4+ T-cell counts and Th1 effector function correlate with active TB, but not co-infection, in HIV-1-infected persons." (PMID 26959228, 2016). "HIV-specific CD4+ and CD8+ T cell functionality was found to be lower in co-infection with LTBI, and to a greater extent TB, as compared to HIV mono-infection." (PMID 25781898, 2015). "We examined the effect of CMV co-infection and presence of CMV viremia on longitudinal reconstitution of CD4+ and CD8+ T-cell subsets in a cohort of ART-exposed PHIV+ children with severe disease who initiated a more aggressive cART regimen." (PMID 25794163, 2015). "We aimed to assess the impact of co-infection with Mycobacterium tuberculosis (MTB) on HIV-specific CD8+ and CD4+ T cell function." (PMID 25781898, 2015). "By considering the highly prevalent intestinal helminths, the baseline mean CD4+ T-cell count in Ascariasis, hookworm, mixed and all types’ parasite/HIV co-infection were recorded and compared with different intervals after post antihelminthic treatment." (PMID 26415705, 2015). "Patients with >10 ml/min/1.73 m2 decrement in eGFR had higher baseline eGFR (p<0.0001), lower CD4 count (p = 0.0058), had more frequent HBV co-infection (p = 0.0070), and had longer exposure to TDF (p<0.0001), compared to those without decrement in eGFR." (PMID 26535588, 2015). "Here we developed a novel in vitro “co-infection” model where HCV and HIV-1 concurrently replicate in their respective main host target cells—human hepatocytes and CD4+ T-lymphocytes." (PMID 26263487, 2015). "We did not observe an association between NLR and PLR serum levels and risk of solid NADC in HIV-infected patients after adjusting for age, gender, CD4 cell count, presence of HBV and or HCV co-infection and intravenous drug use." (PMID 26442127, 2015). "The CD4 count recovery was less pronounced for both co-infections, but only statistically significant for HBV co-infection." (PMID 24533106, 2014). "This study also observed that co-infection with Blastocystis and HIV created lower CD4 levels and higher IL-2 levels compared to the other co-infections with parasites." (PMID 24883113, 2014). "This study investigated the effect of human immunodeficiency virus (HIV) co-infection, HIV viral load and CD4 count on the HR-HPV viral load; and also investigated the predictors of cervical abnormalities." (PMID 24484380, 2014). "No factor was found to be predictive of the presence of MGUS in particular age, CD4, HBV/HCV co-infection, viral load or ART." (PMID 25394153, 2014).
co-infection (continued). "Awareness of HIV status is important at the time of cancer diagnosis or cancer recurrence to avoid treatment-related complications from co-infection with HIV, drug interactions, potential effects of chemotherapy on the CD4 cell count, and HIV viral load." (PMID 25393748, 2014). "Here, we show significant increases in the frequency of systemic CD4+ T cells and effector T cells in MLN of co-infected animals, suggesting increased immune activation following co-infection." (PMID 24433309, 2014). "Data on demographic features (age, ethnicity, country of origin) and clinical/laboratory parameters were collected from clinical files (HIV subtype, CD4+ cell count, CD4+ nadir, viral load (VL), HBV/HCV co-infection and ART)." (PMID 25397570, 2014). "However, in the HCV-co-infected group, the level of CD4+ negatively associated to IL-27, thereby meaning that under the HCV co-infection, the anti-HIV feedback arc set might be interrupted, which might result in the uncontrolled or less effective suppression of HIV replication." (PMID 24816922, 2014). "Mean CD4 counts for mono-infection and HIV-HBV coinfection groups were 392.3 cells/mm3 and 323.0 cells/mm3, respectively." (PMID 25462190, 2014). "In HIV-VL co-infection with disseminated, diffuse, or generalized cutaneous leishmaniasis, the clinical syndrome is similar to DCL but the CD4 count is low (usually <200/mm3) and the LST is usually negative." (PMID 25412435, 2014). "Our findings show that HCV co-infection altered the correlations between HIV viral loads, IL-27 titers and CD4+ T cell counts." (PMID 24816922, 2014). "This evolution was compared with different variables such as duration of HIV/HCV coinfection, gender, age, previous treatment for HCV, HCV genotype, CD4 lymphocyte counts and the cART employed at the basal test." (PMID 25394140, 2014). "Initiation of anti-retroviral therapy in patients with HIV-TB co-infection may result in immune reconstitution inflammatory syndrome (TB-IRIS), a disorder associated with increased immunopathology due to unfettered inflammation after CD4+ T-cell reconstitution." (PMID 25275318, 2014). "By comparing with HCV and HCV/HIV co-infection, HIV infection displayed the great impact on gene expression profile of CD4+ T cells." (PMID 24520951, 2014). "In patients with HIV/HCV co-infection, the expression of HMOX1 was lower in patients with lower lymphocyte CD4 count and higher HIV viral load." (PMID 24752012, 2014). "CD4 recovery was lower in both HBV and HCV co-infection but only statistically significant for HBV (P<0.001)." (PMID 24533106, 2014). "Our finding was in agreement with researchers who concluded that even though HAART suppresses HIV and increase CD4+ count response, however, it is affected by the presence of HCV co-infection." (PMID 23679118, 2013). "Qualitative and quantitative assessment of recorded CD4 counts, receipt of prophylaxis and antiretrovirals, sensitivity and specificity of clinical signs and symptoms for PCP, co-infection with other pathogens, and case fatality (117 studies)." (PMID 23936365, 2013). "These CD8+ effector functional subsets were therefore related to mycobacterial load analogously to equivalent CD4+ subsets, but the impact of HIV coinfection was more profound." (PMID 23966657, 2013). "In order to remove the possible confounding effect of HCV infection, only 386 subjects (excluding 9 who tested positive for HCV) were tested for the effect of HIV-HBV co-infection on WHO clinical stage, CD4 counts and CD4%, viral load, and ALT." (PMID 23691352, 2013). "We analyzed the cytokines, CD4+T cell levels and viral loads to determine the immune environment in HIV-TB co-infection." (PMID 23936398, 2013). "Raised levels of liver enzymes and lowered mean CD4 counts were seen in HIV-HBV, HIV-HCV and HIV-HBV-HCV co-infections." (PMID 23721493, 2013).
co-infection (continued). "The low sensitivity of FM for HIV-positive individuals particularly those with low CD4 T cell counts, will limit the number of additional patients found by LED FM in countries with high rates of HIV co-infection." (PMID 24039780, 2013). "In the case of HTLV-1 co-infection, high frequencies of activated HTLV-1-infected CD4+ T cells can give a boost to HIV-1 replication." (PMID 24391628, 2013). "The CD4+ and CD8+ recovery of co-infected group 2 was impaired by the co-infection of HCV despite the presence of HAART (CD4+: 148 Vs 343; P < 0.003 and CD8+: 1104 Vs 1259; P < 0.004) at the baseline and the last (fourth year)." (PMID 23679118, 2013). "The possibility of involving HHV-6 in the treatment of HIV has been supported by not only the fact that HHV-6 infects CD4+ T cells, which are target cells of HIV infection, but also by reports that co-infection with HHV-6 and HIV inhibited the increase of HIV." (PMID 23409116, 2013). "Critical risk factors for inadequate recovery were older age (p = 0.001) and nadir CD4 cell count at ART initiation (p<0.0001), while concurrent TB co-infection, BMI, baseline hemoglobin, gender and antiretroviral regimen were not significant risk factors." (PMID 22348047, 2012). "Frequencies of CD4 and CD8 T cells were significantly altered upon co-infection in all three organs when compared to mice infected with M. tuberculosis alone." (PMID 23110184, 2012). "Several studies reported a reduced CD4+ T-cell count recovery in patients with HIV and HCV co-infection with respect to patients with HIV alone." (PMID 22703595, 2012). "Among the 14 patients with HIV co-infection, the median (interquartile range [IQR]) CD4 cell count at the start of MDR-TB treatment was 486.5 (49.3–714.8) cells/mm3." (PMID 22629356, 2012). "We add to this literature the finding that percentages of activated CD4+ and CD8+ T cells increased with co-infection." (PMID 21909439, 2011). "Independent risk factors for DAIDS Grade 3/4 TEs include TPV/r treatment, co-infection with hepatitis B and/or C, DAIDS grade >1 TE and CD4+ > 200 cells/mm3 at baseline." (PMID 20003457, 2009). "In the immediate period following co-infection with SIV, there was a slight proliferative response by CD4+ T cells and memory CCR5+ CD4+ T cells to the following parasitemia." (PMID 19774084, 2009). "We also noted increased proportions of CD4+CD25+FoxP3+ regulatory T cells in patients with S. stercoralis and HTLV-1 co-infection compared to either normal controls or patients infected with either HTLV-1 or S. stercoralis only." (PMID 19513105, 2009). "Modulation of CD4+ and CD8+ T cells occurs during P. cynomolgi parasitemia, and co-infection alters these T-cell subset dynamics." (PMID 19774084, 2009). "In HCV/HIV co-infection, it is possible that intra-hepatic HCV-specific CD4+ T-cells become infected with HIV and recruit HIV-specific immune responses to this site." (PMID 18941622, 2008). "In co-infection, intra-hepatic HIV-specific CD8+ and CD4+ T-cells producing IFN-γ and TNF-α were detected and were comparable in frequency to those that were HCV-specific." (PMID 18941622, 2008). "Our findings revealed that co-infection with T. solium significantly influenced immune responses, with TNF-α levels showing a strong negative association with CD4 counts, while this association was positively modulated by CC status." (PMID 40046043, 2025). "Also, a significant rise in CD4 counts was observed in both the groups receiving ART, but the rise was significantly higher among the HIV-only group as compared to the HIV-TB co-infection group." (PMID 40771827, 2025). "Additionally, DosR-specific IL-10 production by CD8+ T cells was strongly and negatively correlated with activation on naïve CD4+ T cells (r = −0.6730, p = 0.0006), indicative of a suppressive milieu accompanying HLTBI co-infection." (PMID 41148837, 2025).